INS (insulin)
Diseases named in the same sentence as INS in open-access papers (continued):
Sharing a sentence is not in itself a finding about the gene and the disease.
Insulin resistance (continued). "Insulin resistance (IR) is defined physiologically as a state of reduced sensitivity or responsiveness in insulin‐targeting tissues to insulin and is considered the pathogenic driver of a spectrum of chronic diseases, such as Type 2 diabetes and hypertension." (PMID 40245241, 2025). "One of the critical mechanisms underlying insulin resistance is the impairment of insulin signaling via IRS-1." (PMID 39796627, 2025). "Previous experimental studies identified that greater insulin resistance is associated with increased fasting insulin in a non‐linear relationship." (PMID 39797595, 2025). "Recent studies have shown that several non-insulin-based insulin resistance (NI-IR) indices are associated with hypertension and various cardiovascular diseases, serving as independent predictors of cardiovascular mortality." (PMID 40778272, 2025). "Serum cortisol is associated with insulin secretion, and the plasma aldosterone concentration is associated with insulin resistance in patients with untreated type 2 diabetes." (PMID 40296149, 2025). "Other proinflammatory cytokines implicated in the impairment of insulin signaling leading to insulin resistance in the liver and adipose include IL-1β and IL-6." (PMID 40985048, 2025). "We propose a synergistic model wherein obesity exacerbates insulin resistance and lowers vitamin D bioavailability; insulin resistance promotes androgen excess; and vitamin D deficiency contributes to both insulin dysfunction and androgen production." (PMID 40868057, 2025). "It is primarily associated with reduced insulin sensitivity (insulin resistance) and abnormal β-cell function." (PMID 41255514, 2025). "Isolated fasting hyperglycemia has been linked to increased insulin resistance, maternal obesity, increased need for additional insulin therapy, risk of neonatal macrosomia, and poor glycemic control." (PMID 40569563, 2025). "Estrogen deficiency leads to pathway-selective hepatic insulin resistance, where insulin is able to stimulate fatty acid synthesis but unable to suppress hepatic glucose production." (PMID 40522859, 2025). "CNIs have diabetogenic potential and can cause pancreatic islet cell damage, decreased insulin secretion, and peripheral insulin resistance." (PMID 40701574, 2025). "In conclusion, our study highlights the pivotal role of cPLA2 in regulating Cav-1 function and insulin signaling in AD, offering insights into potential therapeutic targets for mitigating insulin resistance associated with the disease." (PMID 41280311, 2025). "Among premenopausal women, breast cancer is often associated with factors such as high insulin levels and insulin resistance." (PMID 39235717, 2025). "Loss of ACOT4 in mice can disrupt insulin signaling and exacerbate insulin resistance induced by a high-fat diet." (PMID 40941321, 2025). "Researchers attributed the cause of the decrease in the fat content after adding SGLT-2 inhibitors to the change in the glucose and insulin levels associated with the improvement in insulin resistance." (PMID 40085410, 2025). "Studies have shown that vitamin D deficiency is strongly associated with insulin resistance, and supplementing with vitamin D can improve insulin sensitivity." (PMID 40626218, 2025). "In contrast, IGT is associated with insulin resistance in muscle tissue and a delayed (second‐phase) insulin secretion in response to food intake." (PMID 40548186, 2025). "The prolonged elevation of blood glucose levels damages insulin signaling pathways, which causes insulin resistance to worsen." (PMID 40225541, 2025). "A major contributing factor to the development of T2DM is insulin resistance, which is caused by these cytokines interfering with insulin signaling pathways." (PMID 40565268, 2025). "Since elevated lactate concentrations are produced by adipose tissue during obesity and are closely linked with insulin resistance, these reductions further confirm the improved tissue responsiveness to insulin." (PMID 41471798, 2025).
Insulin resistance (continued). "Variants in IRS1 can disrupt the insulin signaling pathway, leading to insulin resistance, a hallmark of T2D." (PMID 40862129, 2025). "Atypical antipsychotics are also linked to elevated insulin levels and insulin resistance, and the rs3813929 polymorphism can serve as a diagnostic marker for antipsychotic-induced insulin resistance." (PMID 39966797, 2025). "This process further decreases cellular ATP levels, impacting the ability of insulin‐stimulated cells to uptake glucose and increasing the risk of developing insulin resistance." (PMID 40599237, 2025). "We found associations between genetic variants linked with the H8 haplotype and insulin resistance, measured through insulin levels and the HOMA index." (PMID 40868161, 2025). "Disrupted lipid metabolism leads to excess free fatty acids (FFAs) in the blood, impairing insulin signaling and causing insulin resistance—a key factor in T2D development." (PMID 40376582, 2025). "Insulin sensitivity readily improves upon liver fat content reduction as excess liver fat causes insulin resistance." (PMID 40034298, 2025). "AGEs inhibitors can restore insulin sensitivity and partially mitigate the insulin resistance caused by AGEs-mediated downregulation of insulin signaling transduction in skeletal muscle." (PMID 41551513, 2025). "Glucocorticoids can also cause insulin resistance, manifesting as increased insulin secretion; thus, high insulin levels indirectly cause an increase in leptin levels." (PMID 40417460, 2025). "Myocytes with insulin resistance are deficient in signal transmission, which reduces insulin’s ability to stimulate the GLUT4 transporter and glycogen synthesis." (PMID 41012462, 2025). "Higher ND6 was associated with greater insulin resistance and lower insulin sensitivity, particularly in the low-inflammation group." (PMID 41156500, 2025). "Insulin resistance causes human hepatic de novo lipogenesis, which increases liver ceramide and lipid accumulation and decreases insulin sensitivity." (PMID 40141412, 2025). "According to some authors, childhood obesity is the main driver for impaired insulin sensitivity, strongly linked to MetS, with evidence showing weight gain exacerbating insulin resistance and weight loss improving it." (PMID 40332421, 2025). "Animal studies have demonstrated that GIPR agonists can ameliorate insulin resistance independently of body weight changes and enhanced insulin sensitivity in white adipose tissue is associated with reduced hepatic lipid deposition." (PMID 41431568, 2025). "Dysfunction of islet hormones constitutes a significant pathogenic factor in the development of T2D, which is characterized by hyperglycemia, insulin resistance, defective insulin secretion, and loss of β‐cell function and mass." (PMID 40919135, 2025). "Recently, it was established that gut bacteria associated with insulin sensitivity and insulin resistance exhibited different patterns of carbohydrate metabolism." (PMID 41514592, 2025). "The association of obesity with insulin resistance is also known to be linked to inflammatory, neural, and endocrine processes that affect the sensitivity of organs to insulin levels." (PMID 40289934, 2025). "Because deregulated nutrient sensing is a hallmark of aging with insulin signaling decreasing in both physiological and accelerated aging, it is unsurprising that associations suggesting insulin resistance are found in biologically older individuals." (PMID 40323280, 2025). "Elevated levels of SeP have been associated with impaired insulin signaling and glucose homeostasis, contributing to systemic insulin resistance." (PMID 41341131, 2025). "The substantial decrease in TDD of insulin observed after the initiation of tirzepatide therapy was attributed to the weight loss and decreased insulin resistance induced by tirzepatide." (PMID 40004833, 2025).
Insulin resistance (continued). "Adiponectin, an adipose tissue-derived insulin sensitizer, is a key component of the interrelationship between adiposity and insulin resistance and is a significant risk factor for T2D." (PMID 40843379, 2025). "Meanwhile, central insulin resistance is thought to underlie cardiometabolic diseases due to the important role of insulin in brain circuits that control food intake and voluntary activity." (PMID 40881124, 2025). "Insulin resistance, in turn, is a key feature of type 2 diabetes and has been implicated in amyloid-β accumulation and neurodegeneration via its impact on insulin signaling in the brain." (PMID 41160510, 2025). "Ferroptosis in the liver, fat, and muscle has been demonstrated to cause insulin resistance, whereas ferroptosis in pancreatic beta cells has been demonstrated to result in reduced insulin production." (PMID 40589410, 2025). "Conversely, aged obese mice exhibited diminished microvessel recruitment in response to insulin, suggesting a potential connection between obesity-associated insulin resistance, and impaired insulin-mediated microvascular dilation." (PMID 40522530, 2025). "In type-2 diabetes, impaired oxidative phosphorylation and insulin release is linked to insulin resistance (IR)." (PMID 40791990, 2025). "Insulin resistance is also a significant risk factor associated with obesity and overnutrition, which disrupts normal metabolic function in key insulin-responsive tissues, including the liver, skeletal muscle, and adipose tissue." (PMID 40650275, 2025). "Type 2 diabetes is caused by a complex combination of genetic and environmental factors and is associated with obesity, insulin resistance, and islet dysfunction, including impaired glucose-stimulated insulin secretion (GSIS)." (PMID 41373704, 2025). "According to a series of animal experiments, zinc deficient rats show peripheral insulin resistance, and zinc supplementation improves insulin sensitivity to a certain extent." (PMID 40248148, 2025). "In GDM, insulin resistance is closely linked to deficient insulin secretion by both the pancreatic beta cells and the adipose tissue of pregnant women." (PMID 40724491, 2025). "Studies suggest that while palmitic acid contributes to the development of insulin resistance, oleic acid benefits the cells and lessens the weakening of the insulin signaling pathway caused by palmitic acid." (PMID 41409453, 2025). "Type 2 diabetes (T2D) is a multifactorial disease caused by insulin resistance and impaired insulin secretion from pancreatic β-cells, but the precise mechanisms remain to be elucidated." (PMID 40036227, 2025). "Our research demonstrates that changes in glycosylation affect insulin signaling pathways, exacerbating insulin resistance: a hallmark of PCOS." (PMID 40375948, 2025). "While its inhibition has been associated with exacerbating insulin resistance through increased fatty acid release and inflammatory responses, selective inhibition can also enhance insulin sensitivity by limiting excessive fat accumulation." (PMID 40968148, 2025). "Oestrogen excess increases the risk of breast and endometrial cancers, while insulin resistance activates the insulin/IGF‐1 pathway, promoting colorectal cancer progression." (PMID 40944359, 2025). "Impaired insulin-stimulated glucose uptake in adipocytes and muscle is a hallmark of insulin resistance." (PMID 41157128, 2025). "Insulin secretion depends on calcium signaling channels, and calcium deficiency can lead to insulin resistance and decreased insulin secretion." (PMID 40248148, 2025). "Similar phenotypes including the severe insulin resistance, severe insulin-deficient and obesity-related phenotypes have been replicated using T2DM clinical data obtained from North America, Canada, and Europe." (PMID 39913381, 2025).
Insulin resistance (continued). "The primary causes of type 2 diabetes are insulin resistance, defined by reduced cellular response to insulin, and auto-lipolysis in adipose tissue leading to elevated levels of blood glucose and free fatty acids (FFAs)." (PMID 40943103, 2025). "Our main findings were that ET was significantly associated with higher insulin levels and greater insulin resistance, as measured by HOMA-IR." (PMID 40507127, 2025). "Some mutations cause severe insulin resistance due to dysregulation of insulin signalling or fat metabolism, while some are associated with syndromic features." (PMID 39579208, 2025). "T1DM is characterized by an absolute insulin deficiency caused by pancreatic cell destruction, while T2DM is mainly caused by insulin resistance (IR) and insufficient insulin secretion." (PMID 41001671, 2025). "LPS-induced iNOS drives nitrosylation of IRβ, IRS1, and AKT, which blunts insulin-stimulated phosphorylation and causes insulin resistance." (PMID 41373704, 2025). "Unfortunately, in obesity, this reinforced pancreatic insulin secretion cannot stabilize plasma glucose concentrations due to increasing loss of efficiency, i.e., obese individuals develop insulin resistance." (PMID 41470820, 2025). "In the last years, clinical studies supported the adjunctive use of metformin in people with T1D, particularly for those with insulin resistance, excessive insulin requirements, overweight or high cardiovascular risk." (PMID 41234236, 2025). "Insulin resistance, a feature of metabolic aging, is characterized by elevated fasting blood insulin and glucose levels and has been associated with a decline in cognitive function." (PMID 40137124, 2025). "Given the strong association between central adiposity and insulin resistance, insulin sensitivity has emerged as a key metabolic factor potentially mediating the relationship between adiposity and reproductive outcomes." (PMID 40507609, 2025). "By promoting insulin sensitivity, anthocyanins contribute to the regulation of glucose metabolism and the subsequent reduction of inflammation associated with insulin resistance." (PMID 39136514, 2025). "These parameters are more commonly associated with insulin resistance phenotype of type 2 diabetes, in contrast with the insulin deficient phenotype of type 1 diabetes." (PMID 41408588, 2025). "Insulin resistance (IR), commonly linked with obesity, is a condition of impaired insulin-stimulated glucose uptake in muscle and adipose tissue, together with reduced insulin suppression of hepatic glucose production." (PMID 40585342, 2025). "Skeletal muscle is crucial for insulin-stimulated glucose metabolism, and the loss of skeletal muscle contributes to insulin resistance (IR) and metabolic disturbances." (PMID 41227046, 2025). "Aerobic and resistance training lower oxidative stress and improve glucose metabolism, while muscle-derived IL-6 release during contraction enhances insulin sensitivity and reduces the risk of insulin resistance." (PMID 41515940, 2025). "Insulin resistance, a hallmark of type 2 diabetes (T2D), occurs when cells become less responsive to insulin, leading to elevated blood glucose levels." (PMID 40296787, 2025). "Type 2 diabetes (T2D) is characterized by impaired glucose homeostasis caused by insufficient insulin secretion from pancreatic β cells in the face of insulin resistance." (PMID 40260914, 2025). "Hyperinsulinemia, characterized by excessive circulating insulin, is positively associated with obesity and serves as a clinical indicator in a subset of patients with insulin resistance." (PMID 41048425, 2025). "In GDM, TNF-α is considered an independent risk factor for dysglycemia due to this ability to disrupt insulin action, leading to increased insulin resistance." (PMID 40722699, 2025). "These pro-inflammatory markers interfere with insulin signaling, causing insulin resistance and further worsening the PCOS conditions by increasing androgen production by ovarian theca cells." (PMID 40790236, 2025).
Insulin resistance (continued). "In a large longitudinal cohort of 3325 subjects with an average of 4.2 years of follow-up, changes in triglycerides/HDL were associated with peripheral insulin resistance and 2 h post-load insulin levels." (PMID 40218881, 2025). "Studies have found that insulin resistance is associated with high insulin demand, metabolic disorders and increased mortality." (PMID 40475963, 2025). "The dysfunction or deficiency of GLUT4 can reduce cellular sensitivity to insulin, resulting in insulin resistance and subsequent disturbances in glucose metabolism." (PMID 41011216, 2025). "Glucotoxicity, together with oxidative stress and inflammation, causes type 1 diabetic patients to develop more insulin resistance through the reduction of insulin signaling and glucose uptake." (PMID 40225541, 2025). "By interfering with glucose uptake in cells through abnormalities in the insulin signaling pathway, hyperglycemia causes insulin resistance." (PMID 40869265, 2025). "Incremental increases in TFC were associated with higher fasting glucose, serum insulin, and insulin resistance." (PMID 41383580, 2025). "T1D is characterized by the destruction of beta cells through autoimmune processes, leading to a complete deficiency of insulin, whereas T2D is characterized by insulin resistance, resulting in a relative deficiency of insulin supply." (PMID 40932932, 2025). "Cross-sectional studies have linked altered D5D and D6D activity to insulin resistance, while lifestyle-driven changes in desaturase activity have been associated with shifts in insulin sensitivity." (PMID 40362254, 2025). "The pathophysiological mechanisms of GDM involve impaired insulin secretion and signaling, and its progression is closely associated with multiple interrelated pathological processes, including inflammation, insulin resistance, and oxidative stress." (PMID 41460830, 2025). "To explore the mechanism underlying these effects, we evaluated blood insulin concentration and the homeostatic model assessment of insulin resistance (HOMA-IR)." (PMID 40942080, 2025). "Since the development of insulin immunoassays by Yalow and Berson, it has become clear that type 2 diabetes is often associated with both insulin resistance and relative deficiency." (PMID 40218874, 2025). "The capability of insulin to inhibit hepatic glucose production is compromised in the presence of MASLD-associated insulin resistance, leading to worsening glycemic control." (PMID 40704318, 2025). "These compounds are considered insulin-sensitizing, and therefore, their deficiency leads to insulin resistance." (PMID 41041518, 2025). "Many pro-inflammatory cytokines can also indirectly promote insulin resistance by causing the induction of inflammatory genes, which then alter glucose uptake and insulin sensitivity." (PMID 41012578, 2025). "Conditions of Zn deficiency can increase insulin resistance and inflammation, while 18:1n-9 has been shown to improve insulin sensitivity and exert anti-inflammatory effects in cell culture experiments." (PMID 41518846, 2025). "Patients with HHS, who typically have type 2 diabetes, often exhibit elevated insulin levels due to underlying insulin resistance." (PMID 39913488, 2025). "Insulin resistance is associated with the inability of skeletal muscle cells, adipose tissue and liver to respond adequately to insulin signaling." (PMID 39859258, 2025). "Genetic mutations affecting the insulin signaling pathway, abnormal insulin structures, substance metabolism-related genetic defects, and other related genetic defects are the categories of genetic factors linked to insulin resistance." (PMID 40283443, 2025). "Alter insulin signaling via intercellular communication; pathogenic ELVs impair β-cell function or promote systemic insulin resistance." (PMID 41567335, 2025).